MTOR (mechanistic target of rapamycin kinase)
Diseases named in the same sentence as MTOR in open-access papers (continued):
Sharing a sentence is not in itself a finding about the gene and the disease.
melanoma (continued). "Inhibitors of the PI3K/mTOR pathway and cell cycle are also promising for NF1‐mutant melanoma, as discussed in Section 3.3." (PMID 41492362, 2026). "Here, we report that the mTOR inhibitor sapanisertib improves the efficacy of combined belvarafenib and cobimetinib therapy in NRAS, NF1, and KIT-mutant melanomas." (PMID 42091854, 2026). "Western blot analyses in both in vitro and in vivo demonstrated that BA treatment increased expression of Beclin1 and LC3B proteins, while significantly decreasing expression of PI3K, AKT, mTOR, and MAPK proteins in murine melanoma cells." (PMID 41596235, 2026). "So, reducing the overlapping toxicities of pan‐PI3K/mTOR and MEK inhibitors will be crucial for future clinical research in NRASmut melanoma." (PMID 41492362, 2026). "In melanoma cells, berberine induces autophagic cell death by inactivating the AKT/mTOR signaling pathway." (PMID 40490812, 2025). "Experiments in 3D cultures of melanoma PDE showed that simultaneous inhibition of miR-99b, miR-125a and let-7e affects the tumor immune microenvironment (TIME) while attenuating mTOR pathway activation." (PMID 41550951, 2025). "To investigate the impact of the treatments on key signaling pathways involved in melanoma progression, we evaluated the expression and activation status of ERBB2, BRAF, PI3K, AKT1, and mTOR by immunofluorescence analysis." (PMID 40806647, 2025). "Multiple signaling pathways are dysregulated in melanoma, notably the Ras/RAF/MAPK/ERK and PI3K/AKT/mTOR pathways, which can be targeted therapeutically." (PMID 39941158, 2025). "The melanoma cell line MEWO, characterized by aggressive behavior and high MMP-2 activity, was used as a model to evaluate the effect of mTOR pathway inhibitors on cell invasion." (PMID 40869090, 2025). "In summary, this study highlights the enhanced efficacy of combined PI3K/mTOR and MEK inhibition in limiting invasion and metalloproteinase activity in melanoma." (PMID 40869090, 2025). "This multidimensional approach integrates molecular biology, live-cell imaging, and computational analysis to provide novel insights into how targeting the PI3K/AKT/mTOR and MEK pathways modulates melanoma cell behavior." (PMID 40869090, 2025). "TIG1 suppresses mTOR activity by interacting with VAC14, thereby inhibiting the growth and proliferation of melanoma cells." (PMID 40699636, 2025). "This study provides the first integrated assessment of the effects of mTOR and MEK1/2 inhibitors on molecular markers of EMT and dynamic morphological features in a highly invasive melanoma model." (PMID 40869090, 2025). "Salidroside inhibits melanin synthesis and melanoma development most likely by its antioxidant properties and downregulating the PI3K/Akt/mTOR pathway." (PMID 40708947, 2025). "Principal oncogenic signal transduction in melanoma often engages constitutive Ras/MAPK activation and can co-involve, or recruit, dysregulated PI3K/AKT/mTOR signaling, including in the case of human and canine MM." (PMID 40568110, 2025). "Research indicates that Marsdenia tenacissima extract reduces melanoma cell viability and triggers apoptosis by modulating the PI3K/AKT/mTOR signaling pathway." (PMID 40699827, 2025). "The intracellular PI3K/AKT/mTOR and MAPK/ERK pathways cooperate in tumor growth and are known aberrantly activated in melanoma cells, contributing to enhanced cell proliferation and inhibition of apoptosis." (PMID 41373567, 2025). "In this study, we report for the first time that the SPACA6-hosted miR-99b~125a~let-7e cluster contributes to melanoma cell and tumor resistance to BRAF/MEKi through a mechanism involving the mTOR signaling pathway." (PMID 41550951, 2025). "We investigated the anti-melanoma effects of salidroside in B16F10 cells, zebrafish, and mouse models, and examined the involvement of PI3K/Akt/mTOR signaling in these effects." (PMID 40708947, 2025).
melanoma (continued). "Targeting these pathways, particularly mTOR signaling to overcome the inevitable acquired resistance to BRAF and MEK inhibition in melanoma, has been investigated." (PMID 39941158, 2025). "The mTOR inhibitors rapamycin (sirolimus) and NVP-BEZ235 induce apoptosis and cell cycle arrest in BRAF mutant melanoma cell lines." (PMID 39941158, 2025). "In conclusion, Lico-A demonstrates multi-target anticancer potential in oral squamous cell carcinoma and melanoma through Sp1 suppression, PI3K/AKT pathway blockade, and mTOR pathway modulation." (PMID 41181588, 2025). "Previous research has shown that panduratin A activates protective autophagy in melanoma cells via the adenosine monophosphate-activated protein kinase (AMPK) and mammalian target of rapamycin (mTOR) signaling pathways." (PMID 40076971, 2025). "It will be particularly interesting to dissect the role of PIPP in other cancers such as melanoma, given others have reported that PIPP has oncogenic potential in melanoma via enhanced AKT/mTOR signaling." (PMID 41408399, 2025). "Multiple dysregulated signaling pathways in melanoma, including the Ras/RAF/MAPK/ERK and PI3K/AKT/mTOR pathways, drive tumor progression." (PMID 39941158, 2025). "The largest decreases in in vitro invasion were observed for melanoma cells treated with dual PI3K and mTOR inhibitors: BEZ-235 and Omipalisib." (PMID 40869090, 2025). "Both compounds exhibited favorable binding energies with several targets, including PI3K, AKT1, mTOR, BRAF, and ERBB2, all of which are critical regulators of cell proliferation and survival in melanoma." (PMID 40806647, 2025). "In our study, we evaluated the effect of mTOR inhibitors, alone and in combination with the MEK1/2 inhibitor AS-703026, on MEWO melanoma cell morphology and expression of EMT-related proteins." (PMID 40869090, 2025). "In human melanoma cell line A375, EGCG induces apoptosis via mitochondrial signaling pathway and downregulates autophagy through the AMPK/mTOR and PI3K/AKT/mTOR signaling pathway." (PMID 40490812, 2025). "Dual drug-resistant melanoma cell lines SKMEL28 and WM2664 to MAPK and PI3K/mTOR inhibitors exhibited increased expression of α3β1 and α11β1 integrins." (PMID 40243917, 2025). "After determining that salidroside downregulated the mTOR levels in B16F10 cells, we further examined the effects of salidroside on mTOR expression in melanoma tissues." (PMID 40708947, 2025). "Studies have found that knockdown of B7-H3 in metastatic melanoma tissue increases the sensitivity of melanoma cells to chemotherapy with dacarbazine (DTIC), binimetinib (MEK inhibitor), everolimus (mTOR inhibitor), and triciribine (AKT inhibitor)." (PMID 40519928, 2025). "Functional studies using 3D melanoma PDE cultures in bioreactor, in which miR-99b, miR-125a and let-7e were simultaneously inhibited, further validated their impact in triggering the mTOR pathway promoting an immunosuppressive TME." (PMID 41550951, 2025). "Previously, we have shown LncRNA PURPL directly interacts with ULK1 to promote mTOR-mediated phosphorylation of ULK1 at Ser757 to repress autophagic cell death and promote melanoma cell survival." (PMID 40651979, 2025). "For example, in melanoma models, iNOS-generated NO can reversibly S-nitrosylate the TSC2 protein, disrupting TSC2/TSC1 dimerization, leading to mTOR activation and increased melanoma cell proliferation." (PMID 39737957, 2024). "This review provides insight into the role of CD133 signaling in the PI3K/mTOR pathway which can lead to melanoma progression, drug resistance, and recurrence, and the impact of the CD133/PI3K/AKT/mTOR pathway as a therapeutic target for melanoma treatment." (PMID 38334632, 2024). "Ubiquitin‐specific protease 22 (USP22) stabilizes SIRT1 and activates the PI3K/Akt/mTOR pathway through enhancing SIRT1‐mediated PTEN deacetylation, thereby promoting melanoma metastasis both in vitro and in vivo." (PMID 39135915, 2024).
melanoma (continued). "Although the role of PI3K/AKT/mTOR in melanoma progression and drug resistance is well described, the inhibitors of the PI3K/AKT/mTOR pathway have demonstrated only limited success in clinical trials, particularly when applied as a monotherapy." (PMID 38334632, 2024). "RPPA of the tumor lysates also confirmed increased Igfbp2 in melanoma tumors borne in aged mice, as well as an increase in fatty acid synthesis proteins, p-AKT, and the mTOR pathway." (PMID 39007351, 2024). "In vitro, eucalyptol significantly decreased migration and invasion by inhibiting the PI3K/Akt/mTOR pathway in A431 human SCC cells, A375 human melanoma cells, and B16F10 mouse melanoma cells, respectively." (PMID 38674007, 2024). "Within many options for small signal inhibitors in canine melanoma, MEK inhibitors in combination with PI3K/mTOR inhibitors, such as trametinib and sapanisertib, show promise." (PMID 39408717, 2024). "As is widely documented, the development of melanoma is attributed, in great part, to intensive skin exposure to both UVA and UVB rays that contribute to the dysregulation of the PI3K/AKT/mTOR pathway." (PMID 38334632, 2024). "Inhibition of the PI3K/Akt/mTOR pathway to enhance autophagy and overexpression of Beclin 1, LC3, and LC3-II are also observed in α-mangostin and polyphyllin I in melanoma cells." (PMID 39371094, 2024). "Targeted therapy for melanoma mainly targets the MAPK/ERK and PI3K/AKT/mTOR pathways, the main objective is to inhibit tumor growth and to identify resistance mechanisms." (PMID 39408717, 2024). "This review highlights several key pathways involved in resistance in advanced melanoma, including the PI3K/AKT/mTOR and JAK-STAT pathways, as well as the crucial roles of APCs, MHC molecules, IFN-γ, VEGF, and endothelins, among others." (PMID 39534873, 2024). "For example, tegaserod which is a serotonin receptor 4 (HTR4) agonist is reported to be inducing apoptosis in B16F10 murine melanoma cell line and some human melanoma cell lines by perturbing PI3K/Akt/mTOR pathway." (PMID 38216592, 2024). "So far, different compounds have been developed and reported to impair drug resistance in cancer cells endowed with stem-like traits, including melanoma CSCs, through the suppression of the PI3K/Akt/mTOR signaling cascade." (PMID 39199632, 2024). "As previously reported by our group, SN-MM are characterized by recurrent expression of phosphorylated Akt on melanoma cells from clinical samples, suggesting a relevant role for the activation of the PI3K-Akt-mTOR pathway in these neoplasms." (PMID 38191367, 2024). "Previous studies have documented that in melanoma cells, caffeine has a modulatory effect on the signaling cascades of AMP-activated protein kinase (AMPK), PI3K/Akt, and the mammalian target of rapamycin (mTOR)." (PMID 39064880, 2024). "Mechanistically, ZWINT knockdown decreases the protein expression levels of c-MYC, MTOR, phosphorylated MTOR, pp38, and fibronectin, while c-MYC overexpression reversed the effects on melanoma cell proliferation and migration." (PMID 38950330, 2024). "Our findings corroborate previous studies showing celastrol's inhibitory effects on melanoma cell proliferation, viability, and tumor growth upon inhibition of PI3K and mTOR." (PMID 38771435, 2024). "Juniperus indica Bertol extracts induced melanoma cell apoptosis and synergized with cisplatin by suppressing the AKT/mTOR and MAPK pathways." (PMID 39125994, 2024). "Oleacein in melanoma cells reduces the mRNA expression of c-KIT, K-RAS, and PIK3R3, which are crucial effectors responsible for heightened mTOR activation." (PMID 39203892, 2024).
melanoma (continued). "In general, our work indicated that the transcription factor SPI1 promoted melanoma cell proliferation, metastasis and glycolysis by promoting HK2 expression and activating the AKT1/mTOR signalling pathway." (PMID 37539493, 2023). "Another research study indicated that the treatment of SK-MEL-28 melanoma cells with PXT and MET for 24 h resulted in the activation of AMPK and the mTOR pathway downstream." (PMID 37893061, 2023). "Using gene expression profiling, we aimed to study the components of the PI3K/AKT/mTOR pathway, which is involved in resistance development in BRAF-mutant melanomas." (PMID 37895015, 2023). "Another compound under study in models of melanoma is SKLB-M8, a millepaquine derivative, which appears to block cell proliferation via the AKT/mTOR pathway and appears to down-regulate angiogenesis by regulating ERK1/2 phosphorylation." (PMID 36982349, 2023). "TMZ; rapamycin (RAP), a selective mammalian target of rapamycin (mTOR) inhibitor; and bevacizumab (BVZ), a humanized anti-VEGF monoclonal antibody, were co-loaded in Intralipid® and tested in vivo on the B16-F10 melanoma mouse model." (PMID 36986798, 2023). "SPI1 knockdown restrained melanoma cell proliferation, metastasis and glycolysis by regulating the AKT1/mTOR pathway." (PMID 37539493, 2023). "To gain mechanistic insights into signaling pathways regulating OXPHOS and glycolytic melanoma mDC metabolism, we employed antibodies recognizing the total and phosphorylated forms of AMPK (Thr-183/172) and p-mTOR (Ser-2448)." (PMID 37938561, 2023). "The use of the combination of PI3K inhibitors, mTOR, with the MEK1/2 inhibitor AS703026 resulted in a marked decrease in melanoma cell proliferation." (PMID 37097377, 2023). "Using dCas9-VPR (VP64-p65-Rta), PTEN expression can be reactivated in melanoma cell lines, resulting in the repression of AKT, mTOR, and MAPK oncogenic pathways and increased sensitivity to B-Raf and P13K/mTOR inhibitors." (PMID 37190012, 2023). "In animal models, another compound, VS-5584, was recently tested and was shown to inhibit both mTOR and PI3K in melanoma cells." (PMID 36982349, 2023). "With the downregulation of mTOR and Akt and the overexpression of TSC, fisetin reduced melanoma progression in a 3D melanoma skin model." (PMID 37565061, 2023). "Nav1.6 sodium channel promotes melanoma cell (WM266 and WM115) invasion and proliferation by mTOR-mediated Na+/Ca2+ exchange." (PMID 35162934, 2022). "In the present study, we first showed that Piezo1 was abnormally expressed in melanoma, which accelerated the malignant progression by activating AKT/mTOR signaling." (PMID 36112948, 2022). "In melanoma B16 cells, harmine, an active component of MNZQ, inhibits the phosphorylation of Akt and mTOR, as well as increases the expression of LC3-II and p62 protein, thereby inducing autophagic cell death." (PMID 36104717, 2022). "Apigenin has been shown to activate the cleaved caspase-3 and PARP expression sites, down-regulate the Twist1, p-mTOR, ERK1/2 proteins, deactivate FAK/ERK1/2 pathways and halt the phosphorylation of STAT3 in different melanoma cases." (PMID 35807549, 2022). "In melanoma, HOTAIR also functions as ceRNA for miR-157-3p and activates the c-MET oncogene and the PI3K/AKT/mTOR-signaling pathway, promoting invasion and metastasis." (PMID 35159386, 2022). "The same MAPK and PI3K/AKT/mTOR pathways have been found to be activated in OMM and human melanomas, highlighting the overlap between OMM and specific human melanoma subtypes molecular signature." (PMID 35224082, 2022). "In another study carried out in melanoma models, SKLB-M8, a millepachine derivative, showed inhibition of proliferation and induced apoptosis via AKT/mTOR signaling pathway and inhibited angiogenesis with a decrease in ERK1/2 phosphorylation." (PMID 36428613, 2022).
melanoma (continued). "In melanoma cases, it has been reported that apigenin activates the cleaved caspase-3 and PARP expression sites; downregulates Twist1, MMP-2/9, VEGF, p-mTOR, ERK1/2 proteins, and p-AKT; and deactivate FAK/ERK1/2 pathways." (PMID 35965686, 2022). "However, it was found to demonstrate a connection with the mTOR pathway; treatment of melanoma cells with the flavonoid Licochalcone A resulted in elevated miR-142-3p expression, followed by the inhibition of the target gene Rheb and the suppression of the mTOR signaling pathway." (PMID 35743464, 2022). "To directly test if the PI3K-Akt-mTOR axis is activated in IFNγR1KO melanoma cells, we analyzed p-AKT and p-4E-BP1, functional readouts of mTOR action, and found both were increased." (PMID 36008408, 2022). "In melanoma-related proteomic studies, PI3K/AKT pathway, mTOR pathway, and mitogen-activated protein kinase (MAPK)/ERK pathway are the most frequently mentioned signaling pathways." (PMID 36338621, 2022). "Hyperactivation of PI3K/AKT/mTOR and MAPK/MEK/ERK signaling pathways is commonly observed in many cancers, including triple-negative breast cancer (TNBC) and melanoma." (PMID 35806358, 2022). "This impaired the autophagic process in melanoma both in vitro and in vivo through AMPK activation and inhibition of the mTOR pathway." (PMID 36551529, 2022). "Targeting AKT/mTOR and MAPK pathway at the same time, was shown to reverse the resistance of melanoma cells and further propose a new approach for melanoma treatment." (PMID 35163615, 2022). "It has also been shown that resveratrol suppresses the growth of B16F10 murine melanoma cells and A375 human cells by promoting autophagy and inhibiting the PI3K/AKT/mTOR signaling pathway." (PMID 35458783, 2022). "Recent studies revealed that HIF1α can be induced by different signaling pathways, such as PI3K/Akt/mTOR, RAS/RAF/MEK/ERK, JAK/STAT, and NF-κB pathways controlling melanoma tumor growth, metabolism, motility, and apoptosis evasion." (PMID 35163570, 2022). "We show here that the augmented mTOR pathway represents such a key compensatory mechanism, resulting in JAK1/2 activation in IFNγR1KO melanoma." (PMID 36008408, 2022). "In melanoma A375 and C8161 cell lines, 40 mg of apigenin was found to inhibit the activity of cancer cells via AKT/mTOR signal transduction." (PMID 35807549, 2022). "Activation of mTOR signaling is likely to occur at this stage, since activation of PI3K/Akt has been found in human contiguous nevus-melanoma specimens." (PMID 36077374, 2022). "Apigenin substantially inhibits cell proliferation, invasion, migration, and triggered G2/M phase arrest and death in human melanoma A375 and C8161 cell lines, and reduces the activity of p-ERK1/2, p-AKT, and p-mTOR." (PMID 35807549, 2022). "Metformin, an antidiabetic drug, induces autophagy and apoptosis in melanoma cells (SK-MEL-28, G361, A375, and WM9), reduces mTOR, and increases BECLIN expression, a mechanism similar to our findings in the CHL-1 cells treated with EcTI." (PMID 35566311, 2022). "A phase Ib study (NCT01390818) tested MEK inhibitor pimasertib and PI3K/mTOR inhibitor voxtalisib in patients with advanced solid tumors, including TNBC and BRAFV600-mutant melanoma patients who progressed on BRAF inhibitors." (PMID 35806358, 2022). "Interestingly, upregulated levels of 4E-BPs, which are cancer repressor proteins and mTOR major substrates for phosphorylation warrant further studies to elucidate a concise description of the mode of action of Octpep-1 alone or in combination with other melanoma therapies." (PMID 33672955, 2021). "Our study reveals that mTOR activation is essential for drug resistance of melanoma to MAPK inhibitors, and provides insight into the rewiring of the signaling networks in CR melanoma." (PMID 34304249, 2021). "Specifically, in both A375 and C8161 melanoma cell lines, the apigenin administration promoted the growth arrest via down regulation of the p-ERK1/2, p-AkT and p-mTOR." (PMID 33794890, 2021).